BTK (Bruton tyrosine kinase)
Diseases named in the same sentence as BTK in open-access papers (continued):
Sharing a sentence is not in itself a finding about the gene and the disease.
mantle cell lymphoma (continued). "In contrast, in more aggressive B‐cell malignancies, including diffuse large B cell lymphoma (DLBCL) and mantle cell lymphoma (MCL), responses to single agent BTK inhibitors (BTKi) occur only in subsets of patients and are mostly of brief duration." (PMID 39157626, 2024). "On the other hand, multiple B-cell cancers, such as chronic lymphocytic leukemia (CLL), mantle cell lymphoma (MCL), diffuse large B-cell lymphoma (DLBCL), and acute myeloid leukemia (AML), are linked with the upregulation of BTK." (PMID 36903645, 2023). "2b (Ibrutinib, PCI-32765), the first-in-class BTK inhibitor, is an orally available, highly potent, and irreversible ATP-competitive kinase inhibitor for the treatment of mantle cell lymphoma (MCL) and chronic lymphocytic leukemia (CLL)." (PMID 36770611, 2023). "Orelabrutinib is an oral, irreversible and highly selective BTK inhibitor that has recently been applied in mantle cell lymphoma (MCL) and lymphocytic leukemia patients." (PMID 36003388, 2022). "Bruton tyrosine kinase (BTK) inhibitors that disrupt BCR signaling have received regulatory approvals in therapy of mantle cell lymphoma (MCL)." (PMID 35296646, 2022). "Mutations in key genes of the alternative NF-kB pathway, such as BIRC3, confer resistance to BTK inhibitors in mantle cell lymphoma (MCL), that can be overcome with the addition of NIK inhibitors." (PMID 34202439, 2021). "We also compared the potency of BTK degraders in Mino cells, a BTK dependent mantle cell lymphoma (MCL) cell line." (PMID 32848159, 2020). "Zanubrutinib (BrukinsaTM) is a Bruton’s tyrosine kinase (BTK) inhibitor indicated for the treatment of mantle cell lymphoma (MCL)." (PMID 32050446, 2020). "Ibrutinib is a specific inhibitor of the Bruton kinase (BTK) and it has been recently approved for the therapy of relapsed/refractory mantle cell lymphomas (MCL), chronic lymphocytic leukemia (CLL) and Waldenstrom macroglobulinemia (WM)." (PMID 31921674, 2019). "Despite the development of the novel Bruton tyrosine kinase inhibitor ibrutinib, mantle cell lymphoma (MCL) remains an incurable B-cell non-Hodgkin lymphoma." (PMID 29983879, 2018). "In particular, ibrutinib, previously called PCI-32765, is a potent inhibitor of Bruton tyrosine kinase (Btk), recently approved for the treatment of relapsed mantle cell lymphoma (MCL) and chronic lymphocytic leukemia (CLL)." (PMID 26022368, 2015). "BTK is required for B-cell receptor (BCR) signaling and implicated in the development of the B-cell malignancies including chronic lymphocytic leukemia (CLL), mantle cell lymphoma (MCL), follicular lymphoma (FL), diffuse large B-cell lymphoma (DLBCL) and acute lymphocytic leukemia (ALL)." (PMID 24472371, 2014). "BTK inhibitors (BTK = Bruton’s tyrosine kinase) have revolutionized the treatment of B-cell malignancies, particularly chronic lymphocytic leukemia (CLL) and mantle cell lymphoma, with newer-generation agents offering improved safety profiles." (PMID 41464798, 2025). "Acalabrutinib, a highly selective, potent, covalent Bruton tyrosine kinase inhibitor, was first approved by FDA in 2017 with PML warnings for adult patients with relapsed/refractory mantle cell lymphoma." (PMID 41550941, 2025). "BTK inhibitors, such as Acalabrutinib and Ibrutinib, are FDA‐approved for CLL and mantle cell lymphoma, with Acalabrutinib showing improved specificity." (PMID 40809351, 2025). "NX-2127, developed by Nurix Therapeutics, degrades Bruton’s Tyrosine Kinase (BTK) and is currently in Phase 1 trials for B-cell malignancies, including chronic lymphocytic leukemia (CLL) and mantle cell lymphoma (MCL)." (PMID 40574056, 2025). "Acalabrutinib, the second-generation BTK inhibitor with greater selectivity, has been approved by the FDA for use in previously treated mantle cell lymphoma and newly diagnosed CLL." (PMID 40346640, 2025).
mantle cell lymphoma (continued). "Specifically in mantle cell lymphoma cells, the ROR1-CD19 complex was shown to effectively replace BCR/BTK signaling and promote cell proliferation." (PMID 38376944, 2024). "Zanubrutinib is an inhibitor of both BLK and Bruton’s tyrosine kinase (BTK), targeting BTK for the treatment of multiple hematologic diseases such as mantle cell lymphoma (MCL)." (PMID 38997544, 2024). "Ibrutinib is an FDA-approved irreversible covalent BTK inhibitor that has been used to clinically treat chronic lymphocytic leukemia (CLL) and mantle cell lymphoma (MCL)." (PMID 36830087, 2023). "For example, in mantle cell lymphoma (MCL), lymphoma cells reprogram metabolically toward OXPHOS and glutaminolysis to gain advantage in generating energy and develop drug resistance to Bruton’s tyrosine kinase (BTK) inhibitors." (PMID 37032776, 2023). "One example is the Bruton Tyrosine Kinase (BTK) inhibitor ibrutinib, approved for CLL and mantle cell lymphoma." (PMID 36968995, 2023). "Zanubrutinib is a second-generation TKI of Bruton’s Tyrosine Kinase (BTK) that has been recently introduced and approved by the FDA for several B cell-based blood cancers, including mantle cell lymphoma (MCL)." (PMID 36986876, 2023). "Regulatory authorities have granted approval to treat B-cell malignancies, such as chronic lymphocytic leukemia (CLL) and mantle cell lymphoma (MCL), with multiple small-molecule BTK inhibitors." (PMID 38138527, 2023). "Targeting CSF1R caused abrogation of CD163+ TAMs in mantle cell lymphoma (MCL), irrespective of the sensitivity to BTK inhibitors." (PMID 36578079, 2022). "The introduction of BTK inhibitors as part of the treatment regimen in chronic lymphatic leukemia (CLL), lymphoplasmacytic lymphoma (LPL) and mantle cell lymphoma (MCL) has been very successful." (PMID 36051027, 2022). "Despite their initial effectiveness, these precision medicine strategies are limited by primary resistance in aggressive B-cell lymphoma such as diffuse large B-cell lymphoma (DLBCL) and mantle cell lymphoma (MCL), especially in the case of first generation BTK inhibitors." (PMID 35205606, 2022). "We recently introduced thienopyranone (TP) scaffold-based chemotypes for the combinatorial inhibition of BTK, PI3K-AKT, and BRD4-MYC in a single compound (i.e., SRX3262 and SRX3305) and demonstrate impressive preclinical activity in mantle cell lymphoma (MCL)." (PMID 35743155, 2022). "Ibrutinib, an irreversible BTK inhibitor, was initially approved for the treatment of chronic lymphocytic leukemia (CLL) and mantle cell lymphoma (MCL)." (PMID 34307353, 2021). "Ibrutinib, a bruton tyrosine kinase (BTK) inhibitor which suppresses B-cell receptor signaling, has remarkably improved the outcome of patients with mantle cell lymphoma (MCL)." (PMID 35003920, 2021). "The most studied BTK inhibitor is ibrutinib (PCI-32765), approved for CLL, Waldenström’s macroglobulinemia, mantle cell lymphoma (MCL) (second line), marginal zone lymphoma, and chronic graft-vs-host disease." (PMID 33880738, 2021). "As for patients with R/R mantle cell lymphoma (MCL), the irreversible Bruton’s tyrosine kinase (BTK), which is a critical member of the B-cell receptor signaling pathway, the inhibitor ibrutinib has been approved." (PMID 35008305, 2021). "Ibrutinib was the first BTK inhibitor approved and has indications for treatment of CLL, mantle cell lymphoma (MCL), WM, and marginal zone lymphoma (MZL)." (PMID 34947040, 2021). "Ibrutinib, a first-generation inhibitor of BTK, was approved in 2013 and has shown noteworthy clinical activity in lymphoid malignancies, such as chronic lymphocytic leukaemia (CLL) and mantle cell lymphoma (MCL)." (PMID 34457331, 2021). "The BTK inhibitor Ibr is already approved for the treatment of CLL and mantle cell lymphoma and was further effective in pre-clinical AML studies, multiple myeloma, and pre-BCR B-ALL." (PMID 32684632, 2020).
mantle cell lymphoma (continued). "BCR signaling and its component BTK have direct pathogenic roles in the development of multiple B-cell malignancies, including chronic lymphocytic leukemia (CLL), mantle cell lymphoma (MCL), diffuse large B cell lymphoma (DLBCL), follicular lymphoma (FL) and Waldenstrom’s macroglobulinemia (WM)." (PMID 32455989, 2020). "The Bruton’s Tyrosine Kinase (BTK)-inhibitor ibrutinib is highly active in mantle cell lymphoma (MCL) but may inhibit response to anti-CD20 antibody as previously shown in CLL models." (PMID 31406628, 2019). "Ibrutinib is a first-in-class small molecule inhibitor of Bruton’s tyrosine kinase (BTK) and is used to treat B cell cancers such as mantle cell lymphoma and Waldenström’s macroglobulinemia." (PMID 35582714, 2019). "Acalabrutinib, a second generation BTK inhibitor, has been granted accelerated FDA approval based on preliminary results of a phase II trial in mantle cell lymphoma (NCT02213926)." (PMID 29561760, 2018). "The BTK inhibitor ibrutinib has been approved for lymphomas such as CLL, mantle cell lymphoma and Waldenström’s disease that critically depend on constitutively activated BCR signaling." (PMID 29108275, 2017). "Ibrutinib is a BTK inhibitor approved for treatment of CLL, mantle cell lymphoma and Waldenström's macroglobulinemia." (PMID 28178345, 2017). "Here, we focus on one such targeted agent, the Bruton’s tyrosine kinase (BTK) inhibitor ibrutinib (Imbruvica), and implications for its use in the treatment of mantle cell lymphoma (MCL) and chronic lymphocytic leukemia (CLL)." (PMID 27069735, 2015). "Bruton’s tyrosine kinase (BTK) inhibitors (BTKi) have been developed since 1999 and ibrutinib was the first in class drug, initially approved for treating relapsed/refractory Mantle cell Lymphoma." (PMID 41425555, 2025). "Bruton’s tyrosine kinase (BTK) is associated with the BCR, and BTK inhibitors have been approved for use in chronic lymphocytic leukemia (CLL) and mantle cell lymphomas but have not been rigorously evaluated in resistant B-ALL." (PMID 38376944, 2024). "Mantle cell lymphoma (MCL) is a rare B-cell non-Hodgkin lymphoma subtype which remains incurable despite multimodal approach including chemoimmunotherapy followed by stem cell transplant, targeted approaches such as the BTK inhibitor ibrutinib, and CD19 chimeric antigen receptor (CAR) T cells." (PMID 37740214, 2023). "Over the past decade, BTK inhibitors have become an increasingly popular alternative to chemotherapy-based regimens, particularly in patients who suffer from chronic lymphocytic leukemia (CLL) and mantle cell lymphoma (MCL)." (PMID 37446136, 2023). "Bruton’s tyrosine kinase (BTK) inhibitors such as zanubrutinib and acalabrutinib are increasingly replacing chemotherapy-based regimens, especially for patients with mantle cell lymphoma (MCL), chronic lymphocytic leukemia (CLL) and small lymphocytic lymphoma (SLL)." (PMID 36299883, 2022). "Given the challenge of treating multi-resistant mantle cell lymphoma patients, this work highlights the potential use of anti-CD52 therapy as consolidation after ibrutinib treatment in patients who responded to the BTK inhibitor to achieve MRD negativity and prolong progression-free survival." (PMID 36587029, 2022). "For example, in CLL, the importance of the BCR pathway was already emphasized prior to the clinical use of BTKi, whereas in mantle cell lymphoma (MCL) and Waldenström’s macroglobulinemia (WM) the dependence of the malignant B cells on BCR and/or BTK was mostly discovered later." (PMID 34177947, 2021). "Ibrutinib (IMBRUVICA®) is an irreversible Bruton tyrosine kinase (BTK) inhibitor indicated as a single-agent or in combination regimens for the treatment of chronic lymphocytic leukemia (CLL), mantle cell lymphoma (MCL) and Waldenström’s macroglobulinaemia (WM)." (PMID 33670575, 2021). "Ibrutinib is Bruton tyrosine kinase inhibitor for treating CLL and Mantle cell lymphoma." (PMID 33739367, 2021).
mantle cell lymphoma (continued). "For example, BTK lies within the pathway controlling α4β1-mediated adhesion in BCR-stimulated cells and can also mediate chemokine-induced migration and homing of normal B, mantle-cell lymphoma and CLL cells." (PMID 25632006, 2015). "Phosphorylation of several kinases downstream of the BCR such as SYK, LYN and BTK have been noted in primary mantle cell lymphoma (MCL) cells, suggesting constitutively activated BCR signaling in MCL." (PMID 37954584, 2023). "The appearance of the BTK inhibitors has dramatically improved the treatment of several B-cell malignancies, such as marginal zone lymphoma, Waldenström macroglobulinemia, chronic lymphocytic leukemia/small lymphocytic lymphoma (CLL/SLL), and mantle cell lymphoma (MCL)." (PMID 36770870, 2023). "Preclinical studies have examined selinexor in combination with the Bruton’s Tyrosine Kinase (BTK) inhibitor zanubrutinib in DLBCL and mantle cell lymphoma (MCL)." (PMID 36671496, 2023). "Whether ASCT can be safely omitted from intensive first‐line therapy that incorporates a Bruton's tyrosine kinase (BTK) inhibitor, is being tested in the European MCL Network TRIANGLE trial (NCT02858258): ASCT after a rituximab/ibrutinib/Ara‐c containing induction in mantle cell lymphoma." (PMID 34821081, 2022). "The first developed BTK inhibitor, ibrutinib, was approved by the US Food and Drug Administration (FDA) in 2013 for patients with relapsed/refractory mantle cell lymphoma (MCL) who had received ≥1 prior therapy." (PMID 34055635, 2021). "Bruton’s tyrosine kinase (BTK) is a key component of the B-cell receptor signaling pathway, and the first-generation BTK inhibitor, ibrutinib, has become a standard of care in chronic lymphocytic leukemia/small lymphocytic lymphoma (CLL/SLL), mantle cell lymphoma, and Waldenström macroglobulinemia." (PMID 31875923, 2020). "As a first-generation BTK inhibitor, ibrutinib was rapidly approved by the US Food and Drug Administration (FDA) for the treatment of CLL/SLL and MCL (mantle cell lymphoma) in 2014 and 2013, respectively." (PMID 33005100, 2020). "BTK is critical for survival and proliferation of various B cell malignancies, such as chronic lymphocytic leukemia (CLL) and mantle cell lymphoma (MCL)." (PMID 26540570, 2015). "Bruton's tyrosine kinase (BTK) inhibitors have revolutionized the treatment landscape for patients with indolent lymphoid malignancies such as chronic lymphocytic leukemia (CLL) and mantle cell lymphoma (MCL)." (PMID 41681842, 2026). "Covalent Bruton tyrosine kinase inhibitors (cBTKis) have played a significant role in the management of several B-cell malignancies, particularly chronic lymphocytic leukemia (CLL) and mantle cell lymphoma (MCL)." (PMID 40845254, 2025). "Orelabrutinib, a BTK inhibitor developed by InnoCare Pharma, was approved by the National Medical Products Administration (NMPA) in December 2020 for treating mantle cell lymphoma (MCL), chronic lymphocytic leukemia (CLL), and small lymphocytic leukemia (SLL)." (PMID 38381215, 2024). "Aberrant BTK signaling plays a critical role in the development of various B-cell malignancies including diffuse large B-cell lymphoma, CLL, mantle cell lymphoma (MCL), Waldenström macroglobulinemia (WM), and marginal zone lymphoma (MZL)." (PMID 37696810, 2023). "Abnormal activity of BTK is observed in a range of B-cell malignancies, including Waldenström macroglobulinemia (WM), chronic lymphocytic leukemia (CLL), and mantle cell lymphoma (MCL)." (PMID 36576659, 2023). "Here, we will focus on the role of existing BTK inhibitors for four malignancies: CLL/SLL, mantle cell lymphoma (MCL), WM, and Richter’s transformation (RT) to set the stage for the current areas of unmet need that availability of pirtobrutinib might fill." (PMID 35747462, 2022).
mantle cell lymphoma (continued). "Thus, ibrutinib was developed to specifically inhibit BTK (although other enzymes are indirectly affected too) and provide a therapeutic effect in malignancies such as CLL, mantle cell lymphoma (MCL), DLBCL, and Waldenström’s macroglobulinemia (WM)." (PMID 36172151, 2022). "BTK inhibitors (BTKi) have replaced several chemotherapy-based regimens in standard of care for some of the B-lineage lymphoid malignancies, especially in patients with CLL and mantle cell lymphoma (MCL)." (PMID 33937249, 2021). "For example, inhibition of BTK, PI3K and SYK through ibrutinib, idelalisib, and fostamatinib, respectively, has been shown to be effective in follicular lymphoma, mantle cell lymphoma (MCL), and chronic lymphocytic leukemia (CLL)." (PMID 29489886, 2018). "The advent of Bruton tyrosine kinase inhibitors (BTKi) revolutionized the management of patients with B-cell lymphoproliferative diseases (BLPD), especially for chronic lymphocytic leukemia (CLL), Waldenstrom macroglobulinemia/lymphoplasmacytic lymphoma (WM/LPL) and mantle cell lymphoma (MCL)." (PMID 37483630, 2023). "Among them, the compound PROTAC 29 showed BTK degradation ability in the human AML cell line MOLM-14 and the B-cell lymphoma cell line Ramos B cells, and this substance was reported effective when the QD was 50 mg/kg in a patient-derived xenograft mice model of mantle cell lymphoma (MCL)." (PMID 36142231, 2022). "Ibrutinib is a first-in-class, once-daily, oral inhibitor of Bruton tyrosine kinase (BTK) approved for the therapy of B cell malignancies including chronic lymphocytic leukemia (CLL), Waldenström macroglobulinemia (WM), marginal zone (MZL), and mantle cell lymphoma (MCL)." (PMID 32483668, 2020). "In 2013, a first‐generation BTK inhibitor, ibrutinib, was first approved by the US FDA for mantle cell lymphoma (MCL), CLL/SLL with or without 17p deletion, waldenström's macroglobulinemia (WM), and MZL." (PMID 36254250, 2022).